H3C6 (H3 clustered histone 6)
Description:
Core component of nucleosome. Nucleosomes wrap and compact DNA into chromatin, limiting DNA accessibility to the cellular machineries which require DNA as a template. Histones thereby play a central role in transcription regulation, DNA repair, DNA replication and chromosomal stability. DNA accessibility is regulated via a complex set of post-translational modifications of histones, also called histone code, and nucleosome remodeling.
Synonyms: H3FD; HIST1H3E; H3/d; H3.1
Gene: Protein-coding gene on chromosome 6 (26,224,199 to 26,227,473, forward strand). Ensembl gene ENSG00000274750.
Subcellular location: Nucleus; Chromosome
Subcellular location (Human Protein Atlas): Nucleoplasm
Pathways (Reactome):
Gene expression (Transcription): B-WICH complex positively regulates rRNA expression; DNA methylation; ERCC6 (CSB) and EHMT2 (G9a) positively regulate rRNA expression; MLL4 and MLL3 complexes regulate expression of PPARG target genes in adipogenesis and hepatic steatosis; NoRC negatively regulates rRNA expression; PRC2 methylates histones and DNA; RNA Polymerase I Promoter Escape; RNA Polymerase I Promoter Opening; RUNX1 regulates genes involved in megakaryocyte differentiation and platelet function; RUNX1 regulates transcription of genes involved in differentiation of HSCs; Regulation of endogenous retroelements by KRAB-ZFP proteins; Regulation of endogenous retroelements by Piwi-interacting RNAs (piRNAs); Regulation of endogenous retroelements by the Human Silencing Hub (HUSH) complex; SIRT1 negatively regulates rRNA expression; Transcriptional regulation by small RNAs
Chromatin organization: CHD1 and CHD2 subfamily; CHD6, CHD7, CHD8, CHD9 subfamily; ChAHP complex assembly; Chromatin modifying enzymes; HATs acetylate histones; HDACs deacetylate histones; HDMs demethylate histones; Interaction of NuRD complexes with transcription factors; NuRD complex assembly; PKMTs methylate histone lysines; RMTs methylate histone arginines
Disease: Defective pyroptosis; Dengue Virus-Host Interactions; HCMV Early Events; HCMV Late Events
Signal Transduction: Activated PKN1 stimulates transcription of AR (androgen receptor) regulated genes KLK2 and KLK3; Estrogen-dependent gene expression; Formation of the beta-catenin:TCF transactivating complex; Pre-NOTCH Transcription and Translation
Developmental Biology: Activation of anterior HOX genes in hindbrain development during early embryogenesis; Chromatin modifications during the maternal to zygotic transition (MZT); Transcriptional regulation of granulopoiesis
Immune System: FXIIa activates plasma kallikrein-kinin system; Interleukin-7 signaling; Regulation of PD-L1(CD274) transcription
and 8 more pathways
Gene Ontology:
Molecular function: cadherin binding; protein binding; structural constituent of chromatin; nucleosomal DNA binding; DNA binding; protein heterodimerization activity
Biological process: epigenetic regulation of gene expression; nucleosome assembly; chromatin organization; heterochromatin formation; telomere organization
Cellular component: chromatin; extracellular exosome; membrane; nucleoplasm; nucleosome; nucleus; protein-containing complex; extracellular region; chromosome
Genetic constraint (gnomAD): Loss-of-function variants: 17 observed, 8.63 expected, observed/expected ratio (o/e) 1.97, 90% interval 1.22 to 1.97. That is too few expected variants to judge how well the gene tolerates losing a copy. Missense variants: 298 observed, 207.01 expected, observed/expected ratio (o/e) 1.44, 90% interval 1.31 to 1.58. Synonymous variants: 169 observed, 79.38 expected, observed/expected ratio (o/e) 2.13.
Homologues: Orthologues: chimpanzee H3C10 (100% identical), macaque H3C6 (100% identical), pig H3C6 (100% identical), Drosophila melanogaster His3:CG33812 (99% identical), zebrafish si:ch1073-153i20.2 (99% identical), zebrafish si:ch211-113a14.20 (99% identical), zebrafish si:ch211-113a14.23 (99% identical), zebrafish si:ch211-113a14.27 (99% identical), zebrafish zgc:173552 (99% identical), Caenorhabditis elegans his-17 (97% identical), Caenorhabditis elegans his-2 (97% identical), Caenorhabditis elegans his-32 (97% identical), and 8 more. Paralogues in human: H3C1 (100% identical), H3C10 (100% identical), H3C11 (100% identical), H3C12 (100% identical), H3C2 (100% identical), H3C3 (100% identical), H3C4 (100% identical), H3C7 (100% identical), H3C8 (100% identical), H3C13 (99% identical), H3C14 (99% identical), H3C15 (99% identical), and 8 more.
Diseases named in the same sentence as H3C6 in open-access papers:
H3C6 is named in the same sentence as 1 disease in open-access papers, as found by Europe PMC text mining. Sharing a sentence is not in itself a finding about the gene and the disease. The quoted sentences say what the papers report.
systemic lupus erythematosus (1 paper, 2025). An autoimmune multi-organ disease typically associated with vasculopathy and autoantibody production. "H3C6 expression exhibited positive correlations with cytosolic DNA sensing, RIG-I-like receptor signaling, and Toll-like receptor signaling pathways, while showing negative correlations with systemic lupus erythematosus and autophagy regulation pathways." (PMID 40703521, 2025).